BRCA1 (BRCA1 DNA repair associated)
Diseases named in the same sentence as BRCA1 in open-access papers (continued):
Sharing a sentence is not in itself a finding about the gene and the disease.
breast cancer (continued). "At the same time, the use of PARP inhibitors (PARPi) in patients with germline BRCA1/2 mutation (gBRCAm) is the standard of care in the metastatic and adjuvant settings of high-risk patients with HER2-negative breast cancer." (PMID 36506043, 2022). "Among other physiological activities, BRCA1 was shown to induce the metabolic reprogramming of breast cancer cells with ensuing reversal of the Warburg effect." (PMID 35432218, 2022). "In this study, we assessed the significance of BRCA1/2 expression in breast cancer using multiple online databases and annotation tools." (PMID 35409110, 2022). "As BRCA1 and BRCA2 play an important role in HRR and breast cancer risk, their interaction with genes included in our study regarding the investigated outcomes would be of great interest for future studies." (PMID 36139526, 2022). "It is possible that BRCAm breast cancers, especially those that are BRCA1, had lower levels of ER expression impacting the decision to proceed with endocrine therapy, however, this data is not available." (PMID 35128817, 2022). "Kaplan–Meier Plotter’s survival analysis showed that the overall survival of breast cancer patients was poor in both BRCA1/2 overexpression." (PMID 35409110, 2022). "On the contrary, the risk of developing basal or luminal A breast cancer was reduced to 81% or 77% for BRCA2 and BRCA1 pathogenic variants, respectively." (PMID 35451682, 2022). "The predicted proportion of breast cancer cases possessing pathogenic germline missense variants in these genes is approximately 0.6%, 0.3%, 0.2%, and 1.3% for ATM, BRCA1, BRCA2, and CHEK2, respectively." (PMID 35585550, 2022). "For female BRCA1/2 carriers, risk-reducing salpingo-oophorectomy (RRSO) decreases the risk of ovarian and breast cancer (BC) by >80% and 50%, respectively, with a 77% reduction in all-cause mortality." (PMID 36548287, 2022). "As TAMs can promote or inhibit tumor growth, we set out to examine the effects of PARP inhibition on TAMs in BRCA1-related breast cancer (BC)." (PMID 36223740, 2022). "HERC2 can physically interact with TUSC4 in breast epithelial cells and breast carcinomas to promote BRCA1 stability." (PMID 35889210, 2022). "Breast cancer (BC) patients with BRCA1/2m had a similar overall survival (OS) to those with wild-type BRCA1/2 (BRCA1/2 wt) across 18 studies." (PMID 35909902, 2022). "It is now estimated that 10–25% of breast carcinomas are associated with HRD, due to BRCA1/2 PV, but also of other genes such as PALB2, ATM, ATR, BARD1, RAD51, BRIP1, or FANC." (PMID 35158866, 2022). "In breast carcinomas, MYC is one of the most frequently dysregulated oncogenes, particularly in BRCA1-mutated, basal-like TNBCs, where MYC amplification is reported in up to 50% of cases." (PMID 36207293, 2022). "For individuals with a CPS such as BRCA1/2 PV carriers, a beneficial effect of a Mediterranean diet was described with a modulation of early breast cancer (BC) penetrance among women aged 18–30 due to body weight reduction of at least 10 pounds." (PMID 36290891, 2022). "The knowledge about BRCA1 and BRCA2 variants is critical to establish public policies for hereditary breast cancer screening in Amerindian groups and populations admixed with them, such as the Brazilian population." (PMID 33499154, 2021). "The ternary complex formation protects cells from DNA damage by promoting DNA repair, and supports the growth of BRCA1-null mammary tumors." (PMID 34976832, 2021).
breast cancer (continued). "One investigation studied the effect of an ADSC line in which BRCA1 was eliminated using the CRISPR/Cas9 technique on the interaction with wildtype MDA-MB-231 breast cancer cells." (PMID 34228231, 2021). "The present meta-analysis showed that BRCA1 gene hypermethylation should be suspected in all breast cancer patients with advanced disease stages, positive lymph nodes, and premenopausal age at diagnosis." (PMID 33808555, 2021). "Around 10%–20% of EOBC cases are hereditary BRCA1 and BRCA2 are the most common mutated genes related to breast cancer since their discovery in the early 1990s." (PMID 33807872, 2021). "We also analyzed survival of mammary tumor cell lines harboring Brca1 mutants following exposure to radiation, demonstrating that these cells exhibited radiation hypersensitivity similar to that of MCF7 cells." (PMID 33767581, 2021). "BRCA1 is a tumor suppressor gene whose structural and functional abnormalities are closely related to the incidence of breast cancer." (PMID 33772032, 2021). "In a German study that aimed to evaluate the efficacy of US for the early detection of breast cancer in BRCA1/2 carriers screened by semi-annual US in combination with annual MMG and MRI, 3 of 27 (11.1%) detected tumors were found in the semi-annual US." (PMID 34674065, 2021). "Instead, the posttranslational modifications of cell cycle regulators and the estrogen receptor α (ERα), as well as other breast cancer-related proteins, support an additional tumor-suppressive role of BRCA1/BARD1." (PMID 34638302, 2021). "Other than BRCA1 and BRCA2, inherited mutations in about a dozen other genes are also associated with increased breast cancer risk." (PMID 33893322, 2021). "A high prevalence rate of the BRCA1:c.4964_4982del19 was found in familial breast cancer cases from Calabria suggesting a possible founder effect." (PMID 33573335, 2021). "Deleterious variants in BRCA1 or BRCA2, either germline or somatic, are most frequently observed in ovarian cancer (13.8%), castrate-resistant prostate cancer (11.8%), and breast cancer (6.8%), but can occur in many other cancer types as well." (PMID 34067105, 2021). "We showed significant albeit modest associations among both BRCA1 and BRCA2 heterozygotes between the PRS and contralateral breast cancer risk." (PMID 34113011, 2021). "In this study, we retrospectively analyzed the data from 1019 women affected with breast cancer with BRCA1/2 PVs." (PMID 33573335, 2021). "Germline and somatic BRCA1/2 and ATR were each significantly associated with higher SNV and indel neoantigen loads in breast cancer (FDR < 1.4 × 10−7)." (PMID 34095878, 2021). "The estimated lifetime breast cancer risk in an individual with PHTS is between 67–85%, similar to that conferred by germline variants in BRCA1/BRCA2." (PMID 34771713, 2021). "Germline P/LP variants in BRCA1 and BRCA2 accounted for 80% of P/LP variants found in breast cancer and 57% of P/LP variants found in ovarian cancer." (PMID 33649982, 2021). "Of the 9 BRCA1 or BRCA2 gene mutated patient carriers, which were examined in this study, a large proportion had experienced a previous breast cancer." (PMID 34209669, 2021). "This dataset includes several different subtypes of breast cancer (118 triple-negative tumors, 293 ER+/HER2- tumors and 71 HER2+ tumors, as well as 36 tumors with BRCA1 and 39 tumors with BRCA2 mutations)." (PMID 34181655, 2021).
breast cancer (continued). "Additionally, a clinical trial with a double-blinded, placebo control, prospective design in breast cancer patients carrying BRCA1 mutation evaluated whether supplementation with selenium had a beneficial effect in oxidative stress/DNA damage (8-oxodG in cell DNA)." (PMID 33572626, 2021). "The 8 high or moderate risk susceptibility genes accounted for 7.5% of unselected Chinese breast cancer patients in this study (5.2% for BRCA1/2 and 2.3% for the other genes)." (PMID 34606182, 2021). "Existing studies seem to favor BRCA1/BRCA2 as having little effect on the prognosis of breast cancer." (PMID 34198652, 2021). "The study found 10-year survival of 73·4% (67·4–78·5) for BRCA1/2 vs 70·1% (67·7–72·3) for non BRCA breast cancer compared to the lower 95% CI of 86.9% in our population." (PMID 34312777, 2021). "According to a study, carriers of BRCA1 and BRCA2 combination, BRCA1, and BRCA2 mutations have a lifetime breast cancer risk of 70%, 24%, and 13%, respectively." (PMID 34376160, 2021). "Consistent with our findings, various previous studies reported that there is a much higher rate of TNBC among BRCA1 mutation carriers and BRCA2-related breast cancer is often luminal." (PMID 34490083, 2021). "The most well-known high-penetrance breast cancer predisposition genes are BRCA1 and BRCA2, each predicting 84% and 56% lifetime breast cancer risk." (PMID 34574977, 2021). "Of 160 cancers with BRCA1/2 mutations, LOH was detected in 90% cases of BRCA1 positivity and 54% cases of BRCA2 positivity in breast cancer, and in 93% cases of BRCA1 positivity and 84% cases of BRCA2 positivity in ovarian cancer." (PMID 32862296, 2021). "Germline mutations in BRCA1 and BRCA2 genes account for about 5–10% of all breast cancers and 10–18% of all EOCs." (PMID 34943916, 2021). "BRCA1 and BRCA2 mutations are most prevalent in hereditary breast cancer and are associated with increased risk of breast and ovarian cancer." (PMID 34439348, 2021). "A relatively high frequency of contralateral breast cancer and ovarian cancer occurrence was observed among BRCA carriers and was more frequent in patients carrying BRCA1 mutations." (PMID 34490083, 2021). "Founder mutations have been reported in BRCA1 and BCRA2 in different ethnic groups with inherited breast cancer." (PMID 35096615, 2021). "In contrast to wild-type BRCA1, the expression of a breast cancer-related mutant leads to increased ROS levels, suggesting a dominant-negative effect." (PMID 34638302, 2021). "This has been further demonstrated in a mouse mammary tumor model with specific knock-out of Brca1 in the mammary gland." (PMID 33498875, 2021). "BRCA1 dysfunction is regarded as a drivers of basal-like breast cancer as well as a subgroup of TNBC." (PMID 33498875, 2021). "Two recent studies in 64 791 and 113 927 women respectively confirmed that mutations in HR genes BRCA1, BRCA2, PALB2, BARD1, RAD51C and RAD51D correlate with increased breast cancer incidence." (PMID 34316706, 2021). "Here, we show that breast cancer patients whose tumors show high levels of cyclin E expression have a higher prevalence of BRCA1/2 alterations and have the worst clinical outcomes." (PMID 33916118, 2021). "Mutations in breast cancer type 1 susceptibility protein (BRCA1) and BRCA2 genes are associated with a high risk of SPM for breast cancer or ovarian cancer." (PMID 34395291, 2021). "It is also involved in BRCA1 downregulation, one key protein with a role in breast cancer tumorigenesis." (PMID 33925616, 2021). "Of the BRCA1 carriers, 236 (50.4%) had prior or prospective breast cancer with 201 (43%) having chemotherapy." (PMID 33152107, 2021).
breast cancer (continued). "In prior work, a mutational frequency of 0.4% was observed for ATM alterations in 7,675 BRCA1 and BRCA2-negative breast cancer patients in a Chinese population and a mutational frequency range of 0.45 to 1.0% was found in the US and Europe." (PMID 34471951, 2021). "In our study, CRRM was most commonly performed in younger breast cancer patients (p < 0.001) who, amongst BRCA1 and BRCA2 carriers, derive the greatest survival benefit." (PMID 33531640, 2021). "Median number of breast cancer cases in the family was similar between groups, but there was 1.5 extra case in BRCA1 carriers." (PMID 35155181, 2021). "Specifically in breast cancer, AS affects major breast cancer-related proteins, such as the estrogen receptor (ER), BRCA1, and BRCA2, among others." (PMID 34439272, 2021). "A study of 55 Japanese breast cancer patients from unrelated families investigated these patients for novel SNPs in BRCA1 and BRCA2." (PMID 33503928, 2021). "In summary, case-control comparisons yielded high estimates of relative risk for breast cancer, and even higher estimates for TNBC, for BRCA1, BRCA2, and PALB2 among both EA and AA women." (PMID 33479248, 2021). "Detection rates were similar to those with breast cancer only with 8/134 (6%) having a PV beyond BRCA1/2 (PALB2 = 2) and 2/25 (8%) with breast and ovarian double primaries." (PMID 34439310, 2021). "We previously discovered that the majority of p18−/− mice developed CK8+ and ER+ luminal type mammary tumors while most p18−/−;Brca1+/− mice formed mammary tumors that were ER− and CK5+ basal-like tumors expressing mesenchymal markers as well as EMT-TFs." (PMID 33478572, 2021). "The strengths of this study are the combined analysis of germline BRCA1/BRCA2 and somatic PIK3CA mutations in a group of postmenopausal and young patients with breast cancer." (PMID 34287479, 2021). "The highest scorer 1RUT which included Lim domain transcription factor LMO4 (Lim Only) was first identified as a breast cancer autoantigen, which works as a transcriptional factor and interacts with tumor suppressor Breast Cancer protein 1 (BRCA1)." (PMID 33808029, 2021). "Studies suggest that patients with pathogenic mutations (such as BRCA1, BRCA2, ATM or CHEK2) are more prone to have axillary metastasis, related to their highly aggressive breast cancers." (PMID 34945851, 2021). "MYC is a major proto-oncogene in breast cancer, especially for HER2 and BRCA-1 associated cancers that have poor prognoses." (PMID 33996588, 2021). "BRCA1 and BRCA2 genes had highest frequency of PVs among patients with ovarian cancer (5.4% in BRCA1 and 4% in BRCA2) followed by patients with breast cancer (2.1% in BRCA1 and 1.7% in BRCA2)." (PMID 34326862, 2021). "BRCA1 and BRCA2 genes were identified as genetic risk factors for breast cancer, although mutation carriers represent a minority among breast cancer patients." (PMID 34967927, 2021). "Among these, BRCA1, BRCA2, and PALB2 were still classified as high risk, and ATM, BARD1, CHEK2, and RAD51D were still classified as moderate risk breast cancer susceptibility genes in Chinese women." (PMID 34606182, 2021). "Molecular markers, like BRCA1 or BRCA2 (breast cancer gene 1 or 2) germline mutations, are indicators of possible basal-like breast cancer development and are used to determine potential risk and guide treatment." (PMID 34521857, 2021). "Together, these clinical findings are consistent with the results from our mice cohorts; thereby suggesting an opportunity to use murine systems to further explore how BRCA1 interacts with GATA3 to control EMT in breast cancers." (PMID 34373738, 2021). "Women with germline BRCA1/BRCA2 PVs have a cumulative risk by age 80 of 17–44% for developing EOC and 69–72% for developing breast cancer (BC)." (PMID 34503154, 2021).
breast cancer (continued). "BRCA1 knockdown repressed cancer cell growth, and high BRCA1 expression predicted poor relapse-free survival in breast cancer patients." (PMID 33888730, 2021). "For the next common core signaling pathway, the receptor ERBB2, which was mutated in breast cancer, received microenvironment factor CCL28 to activate TF BRCA1 through signaling transduction proteins CDC42 and ARRDC3 in TNBC and non-TNBC." (PMID 33802957, 2021). "Germline alterations resulting in cancer predisposition - for example BRCA1 and BRCA2 variants - increase the risk of breast cancer in humans, and alterations in these genes have also been documented in dogs with mammary tumors." (PMID 33834049, 2021). "Loss of heterozygosity (LOH) of the wild-type allele to accompany hereditary pathogenic variants in BRCA1 or BRCA2 is predicted to lead to loss of function (LOF) of these genes and increases genomic instability during breast cancer development." (PMID 34439109, 2021). "Further subgroup analysis revealed that in case of BRCA1/2 positive breast cancers FPR was 0 % (0/7) and FNR was 18 % (2/11)." (PMID 34233740, 2021). "Mostly, the diagnostics labs report VUS detected in the gene in clinical question, for example a VUS in BRCA1 gene detected in a breast cancer patient." (PMID 33773534, 2021). "Prospective studies on BRCA1 gene methylation status on a large cohort of breast cancer women was strongly awaited." (PMID 33808555, 2021). "BRCA1 and BRCA2 heterozygotes under age 40 at first breast cancer, at the 5th and 95th percentile of the PRS, differed by 10% in 10-year contralateral breast cancer risk." (PMID 34113011, 2021). "The clinical trial was expanded to include other malignancies, including breast cancers with abnormal BRCA1/2 (ClinicalTrials.gov (accessed on 10 March 2021) ID: NCT02719977)." (PMID 33805424, 2021). "Mutations in BRCA1/BRCA2 are recognized as risk factors for breast cancer induction, but the role in breast cancer prognosis is still controversial." (PMID 34198652, 2021). "Germline mutations in BRCA1/2 (gBRCAMUT) are frequently identified in TNBC patients, ranging from 11–20%, in comparison to 5–7% of all breast cancers." (PMID 34959671, 2021). "From an ethical perspective, it would be unconscionable to deny PRS screening to BRCA1/2-negative families with a history of breast cancer." (PMID 34440279, 2021). "BRCA1, specifically, has been shown to strongly impact energy metabolism, fatty acid metabolism, and antioxidative pathways in breast epithelial cells and breast cancer cell lines." (PMID 33898308, 2021). "Of the deaths with BRCA1/2 PVs, 7/16 were unrelated to breast cancer; BRCA1-4/8 [ovarian (n = 2), carcinosarcoma uterus (n = 1), pancreatic (n = 1)], BRCA2-3/8 (ovarian, lung cancer, old-age)." (PMID 34312777, 2021). "In vitro analysis using breast cancer cell lines further identified a mechanism by which ESR1 expression is positively regulated by direct binding of BRCA1 to the ESR1 promoter, being recruited under the regulation of the transcription factor Oct-1." (PMID 35008774, 2021). "Regarding genetics, approximately 10% of male breast cancer patients have BRCA2 mutations, and <1% are accompanied by BRCA1 mutations." (PMID 33725931, 2021). "Among 6113 breast cancer samples from different cohorts collected in cBioPortal, 169 (2.76%) harbored the genetic alterations on BRCA1." (PMID 34815798, 2021).